RBMS3 (RNA binding motif single stranded interacting protein 3)
Diseases named in the same sentence as RBMS3 in open-access papers (continued):
Sharing a sentence is not in itself a finding about the gene and the disease.
colon cancer (continued). "Furthermore, we conducted an exploration into the influence of RBMS3 on the migration and invasion of colon cancer cells using transwell assays, scratch assays, and mouse models of lung metastasis." (PMID 38618967, 2024). "Through differential expression and clinical stage correlation analysis using data from the TCGA and GTEx public databases, we have found that RBMS3 may play a crucial role in colon cancer." (PMID 38618967, 2024). "Furthermore, we examined the expression of RBMS1 and RBMS3 in normal colon tissues and colon cancer using Western blot and qRT‐PCR." (PMID 38618967, 2024). "Hence, these outcomes signify the significant involvement of RBMS3 in regulation of colon cancer cell proliferation." (PMID 38618967, 2024). "Moreover, we determined the expression of RBMS3 in paired colon cancer and adjacent normal tissues through IHC, revealing a marked decrease in the expression of RBMS3 in colon cancer tissues." (PMID 38618967, 2024). "RBMS3 enhances the mRNA stability of LIMS1, which, in turn, impedes the proliferation, migration, and invasion of colon cancer cells." (PMID 38618967, 2024). "The effect of RBMS3 and LIM zinc finger domain 1 (LIMS1) on colon cancer was substantiated via animal models and cellular experiments." (PMID 38618967, 2024). "The discernments delineate RBMS3 as a novel suppressor of cancer via LIMS1, thereby bestowing fresh therapeutic possibilities and illuminating the intricacies of colon cancer." (PMID 38618967, 2024). "To accomplish this, we established colon cancer cell lines (HCT116 and HCT15) with RBMS3 overexpressed and knockdown, which were subsequently confirmed through Western blot and qRT‐PCR." (PMID 38618967, 2024). "We establish that RBMS3 regulates the mRNA stability of LIMS1, consequently modulating LIMS1's expression level and impeding colon cancer progression." (PMID 38618967, 2024). "Furthermore, our study has ascertained that alterations in RBMS3 expression have the ability to impact the stability of LIMS1 mRNA stability, thereby signifying LIMS1's pivotal role as a target gene of RBMS3 in colon cancer." (PMID 38618967, 2024). "Our research has focused on the role of RBMS3, a gene from the RBM family, in colon cancer." (PMID 38618967, 2024). "However, the role of RBMS3 in colon cancer has not been extensively investigated." (PMID 38618967, 2024). "Furthermore, our study has unveiled the mechanistic involvement of RBMS3, acting as a tumor suppressor, in regulating the mRNA stability of LIMS1, thereby influencing its expression level and consequently restoring LIMS1's inhibitory impact on colon cancer cells." (PMID 38618967, 2024).
exfoliation syndrome (1 paper, 2022). An autosomal dominant disorder caused by mutations in the LOXL1 gene, encoding lysyl oxidase homolog 1. "From the moment of the discovery of RBMS3, scientists pointed to the role of this protein and the gene that encodes it in a wide range of pathological processes, including liver fibrosis, osteonecrosis of the jaw (ONJ), and exfoliation syndrome." (PMID 36142783, 2022).
glioma (1 paper, 2023). A benign or malignant brain and spinal cord tumor that arises from glial cells (astrocytes, oligodendrocytes, ependymal cells). "The study demonstrated that RBMS3 expression was significantly and consistently reduced in glioma tissues compared to that in NBTs." (PMID 37968257, 2023). "Kaplan-Meier curve survival analysis demonstrated a worse overall survival in patients with lower expression of RBMS3, which is relevant to recurrent glioma." (PMID 37968257, 2023).
liver fibrosis (1 paper, 2022). "Published papers provide evidence of the wide range of processes in which RBMS3 takes part in, including regulation of embryogenesis, pathogenesis of liver fibrosis, and bisphosphonate-related osteonecrosis of the jaw (BRONJ)." (PMID 36142783, 2022).
lung adenocarcinoma (1 paper, 2023). A carcinoma that arises from the lung and is characterized by the presence of malignant glandular epithelial cells. "Subsequently, we obtained 598 patient samples from the TCGA dataset and compared the expression of RBMS3 in lung adenocarcinoma with normal tissue." (PMID 37781074, 2023). "Our paired analysis revealed a significant decrease in RBMS3 expression in lung adenocarcinoma." (PMID 37781074, 2023).
lung disease (1 paper, 2020). "If it is known, for example, that a patient has the reference RBMS3 allele and the alternate WNT5A allele, this might indicate a highly likelihood of developing severe SSc-related lung disease, and testing and treatment of lung disease could be started early and aggressively." (PMID 31694854, 2020). "For example, rather than attempting to reduce WNT5A expression globally, a specific targeting of its interaction with RBMS3 may provide a novel approach to treating SSc-related lung disease without widespread off-target effects." (PMID 31694854, 2020).
lymph node metastasis (1 paper, 2017). "It further supported the factors of differentiation, depth of invasion, lymph node metastasis and RBMS3 expression to be the independent prognostic factors." (PMID 27902480, 2017).
Macrocephaly (1 paper, 2022). Occipitofrontal (head) circumference greater than 97th centile compared to appropriate, age matched, sex-matched normal standards. "We retrieved from the DECIPHER database de novo <500 kb CNVs reported on patients with macrocephaly; in four cases, a candidate gene for macrocephaly could be pinpointed: a known microcephaly gene–TRAPPC9, and three genes based on their functional roles–RALGAPB, RBMS3, and ZDHHC14." (PMID 36553552, 2022).
osteonecrosis (1 paper, 2022). A none disease characterized by death of bone tissue due to a lack of blood supply. "GWAS studies showed that two SNPs (rs17024608 and rs10510628) in the RBMS3 were associated with a bisphosphonates-induced reduction in collagen formation, osteonecrosis disruption, and bone turnover." (PMID 35456240, 2022).
ovarian tumor (1 paper, 2022). "An additional study implied that the loss of RBMS3 resulted in the development of platinum resistance in ovarian tumor cells." (PMID 35743677, 2022).
papillary thyroid cancer (1 paper, 2022). "The analysis of lncRNA in papillary thyroid cancer revealed that another product of RBMS3’s expression, RBMS3-AS1, is closely associated with a patient’s shorter OS, broadening the variety of tumors in which RBMS3 has the potential to be a diagnostic marker." (PMID 36142783, 2022).
Pca (1 paper, 2022). "The results showed that the higher expression levels of JAZF1, PRDM6, RBMS3, and TSHR were correlated with the poor prognosis of Pca patients." (PMID 35959113, 2022). "In the regulatory networks of target genes of the sDMIRs, we found that JAZF1, PRDM6, RBMS3, and TSHR were correlated with the poor prognosis of PCa patients." (PMID 35959113, 2022).
squamous cell carcinoma (1 paper, 2016). A carcinoma arising from squamous epithelial cells. "Potential tumor suppressor genes, also found in other squamous cell carcinomas, have been discovered in the lost regions 2q33-q37.3 (PLCD4), 3p26.3-q11.1 (RBMS3, PLCD1, and CACNA2D3) and 11q12.2-q25 (CPT1A, CCND1, FGF4/FGF3, and PPP2R1B)." (PMID 26901676, 2016).
systemic sclerosis (1 paper, 2022). A chronic disorder, possibly autoimmune, marked by excessive production of collagen which results in hardening and thickening of body tissues. "Specifically, there is evidence that certain SNPs in the RBMS3 gene are responsible for an increased susceptibility to systemic sclerosis (SSc) and primary Sjögren’s syndrome (PSS)." (PMID 36142783, 2022).
tumor (29 papers, 2008 to 2025). "By searching the literature, we found that the RBM38’s role in the development of PC has been reported, and RBM47 and RBMS3 were closely associated with tumor immunity." (PMID 39741300, 2024). "In vivo experiments showed the loss of RBMS3 to impair the growth of the tumor and its ability to create metastasis." (PMID 36142783, 2022). "Recently, an RBP, the RNA binding motif single stranded interacting protein 3 (RBMS3) is found to be located at 3p24-p23, where is often found deleted or mutated in cancers, suggesting its potential role in tumor suppressing." (PMID 30819235, 2019). "RBMS3 was found to suppress tumor angiogenesis by regulating HIF1α expression, which implicated the strong correlation between RBMS3 and tumor metastasis." (PMID 30819235, 2019). "It was reported that down-regulation of RBMS3 was associated with poor prognosis and tumor angiogenesis in some cancers." (PMID 27902480, 2017). "Increased expression of RBMS3 may prevent the creation of micrometastases that are too small to be picked up in diagnostic imaging and may lead to relapse of tumor." (PMID 36142783, 2022). "The RBMS3 gene was also used in the creation of the tumor-mutation-burden-related signature model." (PMID 36142783, 2022). "Research indicates that when RBMS3 is overexpressed, it can slow tumor growth, reduce the ability of cancer cells to spread, and promote cell death." (PMID 40330466, 2025). "RBMS3, a RNA-binding protein with tumor-suppressing functions, shows reduced expression in epithelial ovarian cancer (EOC), and this decrease is linked to poorer outcomes for patients, such as shorter overall survival and progression-free survival." (PMID 40330466, 2025). "Several oncogenic RBPs, such as HuR and HNRNPs, promote VM and tumour aggressiveness, while others, including RBMS3, act as suppressors of VM." (PMID 40869298, 2025). "Noteworthy, MBNL1 was highly expressed in both tumor and stroma cells, while NOVA1 and RBMS3 were dominantly expressed in tumor stroma." (PMID 39980011, 2025). "RBMS3 is a post-transcription regulator involved in immune evasion by regulating PD-L1, and reduced RBMS3 levels enhance auranofin-induced anti-tumor T-cell responses." (PMID 39998235, 2025). "Additionally, RBMS3 affects the immune environment of tumors by decreasing the presence of certain immune-suppressing cells, such as regulatory T cells, myeloid-derived suppressor cells, and M2 macrophages, which are often associated with supporting tumor growth." (PMID 40330466, 2025). "In vivo experiments further substantiated these findings, revealing that RBMS3 overexpression suppressed tumor cell growth, while its knockdown facilitated it." (PMID 38618967, 2024). "The suppressive effect of RBMS3 is mediated by a domain located at the 3p region of chromosome 3 that generates multiple tumor suppressor genes." (PMID 37803912, 2023). "The analysis of RBMS3 expression can be included as a supplementary category in defining prognosis of patient survival based on the molecular characteristics of the tumor, increasing the accuracy of predictions." (PMID 36769184, 2023). "We provided an analysis of RBMS3 expression in clinical material and cell lines, and presented experimental data supporting the statement of the potential role of RBMS3 expression in tumor stromal cells." (PMID 36769184, 2023). "RBMS3 is a tumor suppressor gene, and downregulation of RBMS3 is correlated with poor prognosis in in various human cancers." (PMID 37803912, 2023).
tumor (continued). "Experimental data point to the downregulation of c-Myc and CDK4 as the mechanism mediating RBMS3’s tumor suppressive gene (TSG) abilities." (PMID 36142783, 2022). "The ectopic expression of RBMS3 proved to have the ability to inhibit tumor growth and foci formation." (PMID 36142783, 2022). "The ectopic expression of RBMS3 results in tumor growth impairment confirmed by foci formation and tumor xenograft formation tests." (PMID 36142783, 2022). "RNA binding motif, single-stranded interacting protein 3 (RBMS3) is a tumor suppressor gene located in this region and mediates cancer angiogenesis." (PMID 27902480, 2017). "Both in vitro (cell growth rate, colony formation in soft agar and foci formation) and in vivo (tumor formation in nude mouse) assays demonstrated that RBMS3 had a strong tumor suppressive potential in NPC cells." (PMID 22957092, 2012). "One candidate tumor suppressor gene, RBMS3, which resides on human chromosome 3p24-3p23, is widely expressed in the embryo as well as in the adult organisms." (PMID 22957092, 2012). "Functional studies using both overexpression and suppression systems demonstrated that RBMS3 has a strong tumor suppressive role in NPC." (PMID 22957092, 2012). "Tumor suppressive function of RBMS3 was studied by cell growth assay, foci formation assay, and tumor xenograft experiment." (PMID 22957092, 2012). "More comprehensive understanding of the tumor suppressive mechanisms of RBMS3 in NPC would provide much more effective therapeutic strategy for the management of NPC patients." (PMID 22957092, 2012). "The protein expression level of RBMS3 was also evaluated in 30 pairs of primary NPCs and non-tumor samples by immunohistochemical staining (IHC)." (PMID 22957092, 2012). "The tumor suppressive potential of RBMS3 was also evaluated by xenograft tumor formation in athymic nude mice." (PMID 22957092, 2012). "Quantitative real-time PCR (qRT-PCR) was performed to evaluate the expression levels of RBMS3 in 15 pairs of primary NPCs and their corresponding non-tumor samples." (PMID 22957092, 2012). "Four NB tumors had deletions in the CDKN2A gene region in 9p and one tumor had a deletion on 3p involving the RBMS3 gene." (PMID 18664255, 2008). "Furthermore, our findings unveil LIM zinc finger domain 1 (LIMS1) as a pivotal gene mediating RBMS3's tumor‐suppressive effect." (PMID 38618967, 2024). "Additionally, our in vivo experiments provided further evidence by showing that the overexpression of RBMS3 inhibited the lung colonization capacities of tumor cells, while the knockdown of RBMS3 promoted it." (PMID 38618967, 2024). "Moreover, RBMS3 plays an essential regulatory role as a tumor suppressor gene in a variety of tumors." (PMID 37968257, 2023). "Therefore, our research aims to clarify the important role of RBMS3 as a mediator in the LKB1/AMPK inhibition of tumor invasion and metastasis." (PMID 37781074, 2023). "One could hypothesize that higher RBMS3 expression eventually leads to the increased apoptosis of platinum-exposed tumor cells, and, in the same way, that it might lead to the increased apoptosis of platinum-exposed cells in the kidneys." (PMID 35743677, 2022). "The RNA binding protein 3 (RBMS3) acts as a tumor suppressor in various cancers." (PMID 30819235, 2019). "In addition, the Cancer Genome Atlas (TCGA) data indicated that RBMS3 had lower expression in tumor tissues than in normal tissues." (PMID 30819235, 2019). "In this study, we investigated the effect of RBMS3 expression on prognosis and tumor angiogenesis in GC and found RBMS3− GC patients were significantly related to poorer prognosis and higher tumor angiogenesis compared with RBMS3+ GC patients, which was consistent with the previous studies." (PMID 27902480, 2017). "The tumor suppressive effects and corresponding mechanisms of RBMS3 were characterized." (PMID 22957092, 2012). "The tumor-suppressive function of RBMS3 was characterized in two NPC cell lines (SUNE1 and CNE2)." (PMID 22957092, 2012).
tumor (continued). "Another data supporting that RBMS3 is a tumor suppressor in NPC was its role in inducing apoptosis." (PMID 22957092, 2012). "A negative correlation of RBMS3 expression in the stromal cells with TNBC, and a positive one with ER- and PR-receptor status of the tumor, may indicate that there is a possibility for RBMS3 to display an antitumor effect depending on the molecular characteristics of the tumor." (PMID 36769184, 2023). "In addition, we implied that RBMS3 might modulate the location of HIF1A and associate with tumor angiogenesis." (PMID 27902480, 2017). "RBMS3 downregulation also has a central role in regulating the EMT and metastasis in other types of tumours, including breast and hepatocellular carcinoma." (PMID 40869298, 2025). "Another study reported data related to RBMS3′s suppression leading to downregulation of cell programmed death ligand-1 (PD-L1) in TNBC, resulting in increased anti-tumor immune activities." (PMID 36769184, 2023). "Researchers provided evidence of the significant downregulation of RBMS3 in NPC cell lines and postoperational tumor specimens." (PMID 36142783, 2022). "The results showed higher tripartite motif containing 71 [TRIM71] expression in BLCA tissues compared to that in non-tumour tissues, while DARS2 and RBMS3 expression levels were downregulated in tumour tissues." (PMID 33685397, 2021). "The correlation between RBMS3 and the expression of EMT markers may indicate a potential role in predicting the metastatic potential of a tumor and may be used by physicians to determine the early transition from local to systemic cancer therapy." (PMID 39329736, 2024). "There are some limitations to targeting RBMS3 mainly concerning the lack of a deep understanding of molecular mechanisms that are responsible for RBMS3 tumor suppressive abilities and the regulation of this properties." (PMID 36142783, 2022). "Moderate or strong nuclear staining of RBMS3 was detected in 30 non-tumor tissues, whereas no or weak nuclear staining of RBMS3 was observed in 24/30 (80.0%) of NPC tumor tissues." (PMID 22957092, 2012). "Furthermore, the box plot showed a highly significant difference in the mean expression levels of RBMS3 between NPC tumors and non-tumor samples (p<0.001)." (PMID 22957092, 2012). "Furthermore, there may exist a currently unknown post-transcriptional mechanism regulating the expression of RBMS3 in the stroma of the tumor, which could explain the grade-dependent expression of RBMS3 and the lack of grade dependency at the protein level." (PMID 36769184, 2023).